IL1B (interleukin 1 beta)
Diseases named in the same sentence as IL1B in open-access papers (continued):
Sharing a sentence is not in itself a finding about the gene and the disease.
bacterial infection (continued). "Lipopolysaccharides (LPSs) from bacterial infections can enhance the inflammatory response by stimulating both IL-6 and IL-1β pathways, exacerbating cardiovascular inflammation and disease progression through increased cytokine production and systemic inflammation." (PMID 39057626, 2024). "However, another study shows the opposite result that YTHDF1 induces proinflammatory IL-1β production in macrophages following bacterial infection." (PMID 38874470, 2024). "Also, IL-1b, which is increased by bacterial infection, exerts its protective action by recruiting the neutrophils to the site of inflammation, induction of chemokines and the stimulation of the Th17 response." (PMID 39081865, 2024). "Furthermore, IL-6, an essential pro-inflammatory cytokine produced by macrophages, contributes to acute immune responses, while IL-1β plays a vital role in initiating and intensifying inflammatory responses to bacterial infections." (PMID 37627631, 2023). "IL-1β is a pro-inflammatory cytokine, which can be synthesized and secreted by a multitude of cell types, with multifunctional attributions and engagement in a variety of host inflammatory and immune responses especially in context of bacterial infections." (PMID 37261344, 2023). "The findings also increase our understanding of how GSDMD versus GSDME cleavage is differentially utilized for IL-1β secretion and regulated cell death responses in neutrophils compared with macrophages, and in bacterial infections where neutrophils are the predominant cell type." (PMID 37730693, 2023). "In addition, since IL-1β plays an essential role in various bacterial infections, we plan to study how ADSCs can be used in other diseases where inflammation plays a key role." (PMID 35871079, 2022). "In addition, a decreased release of LDH and a decreased expression of IL-1β were observed in bacterial infections, suggesting that these compounds prevent an increase in the oxidative stress produced by infections." (PMID 36080235, 2022). "The leading edge genes driving the enrichment of the inflammatory response pathway in response to bacterial infections included several relevant for T‐cell activation (IL1B, CCL5, TNFSF10, GPR183, CD69, SELL), suggesting that cDC2s were undergoing conventional maturation." (PMID 34333764, 2022). "On the other hand, triggered by viral or bacterial infections, the production of TNFα, IL-6, IL-1β, and INFγ may amplify the ER stress in many cell types including macrophages, pancreatic β cells and hepatocytes." (PMID 34834808, 2021). "Thus, in response to bacterial infection, we found the IL-1β and IL-1RA (IL-1 receptor antagonist) plasma levels increased concomitantly." (PMID 34437647, 2021). "Moreover, TAS treatment alleviated mitochondrial damage by nigericin and improved mouse survival from bacterial infection, accompanied by reduced IL-1β levels in vivo." (PMID 33679781, 2021). "However, inflammasomes including AIM2, NLRP3 and NLRC4 are also expressed in neutrophils and involved in IL-1β secretion during bacterial infection." (PMID 34017331, 2021). "Additionally, OnGal8-L overexpression reduced the expression of IL-1β, TNF-α caused by bacterial infection." (PMID 32676073, 2020). "Interestingly, taurine and malate alleviated the expression of Cox-2, IL-1β, IL-6, IL-8, and elevated the expression of C3 after bacterial infection." (PMID 32316833, 2020). "Macrophages polarize to M1 response to kill the invading pathogens (such as Salmonella typhi, Salmonella typhimurium, and Mycobacterium tuberculosis, etc.)by the production of various proinflammatory cytokines including TNF-α, IL-6, and IL-1β in the early stage of bacterial infection." (PMID 33585271, 2020). "Thus, complexes I and II are the major sites of the production of mitochondrial reactive oxygen species (ROS) and pro-inflammatory cytokine IL-1β during bacterial infection, but the exact mechanisms are still matter of investigation." (PMID 32523583, 2020).
bacterial infection (continued). "IL-1β has been shown to play an important role in early host defense against bacterial infections." (PMID 32373120, 2020). "Moreover, evodiamine administration evidently improved survival of mice with lethal bacterial infection, accompanied by increased production of IL-1β and interferon-γ, decreased bacterial load, and dampened liver inflammation." (PMID 30971927, 2019). "Moreover, paclitaxel administration significantly increased the serum levels of IL-1β in the mouse model of bacterial infection." (PMID 30761140, 2019). "IL-1β levels can modulate in response to bacterial infection." (PMID 31847332, 2019). "In the mouse model of bacterial infection, evodiamine efficiently increased the serum levels of IL-1β, TNF-α and IFN-γ, thus potentiating the innate immune responses to enhance the clearance of bacteria and dampening the infiltration of inflammatory cells in the liver." (PMID 30971927, 2019). "Consistent with the in vitro results, intraperitoneal administration of paclitaxel significantly increased serum IL-1β levels, reduced bacterial burden, dampened infiltration of inflammatory cells in the liver, and improved animal survival in a mouse model of bacterial infection." (PMID 30761140, 2019). "IL-1β is one of the most studied pro-inflammatory cytokines for its crucial role in initiating and regulating the immune system, and has been well documented in chickens by LPS injection, infectious bursal disease, and different bacterial infections." (PMID 31412766, 2019). "IL1β is induced by LPS at the early stages of the immune response to bacterial infection." (PMID 30424006, 2018). "Pro-inflammatory cytokines IL-17 and IL-1β play a crucial role in bacterial infections." (PMID 29394269, 2018). "Consequently, induction of inflammasome activation and IL-1β release can intensify the host defense against bacterial infection in murine models." (PMID 27980220, 2017). "Thus, studies regarding the process leading to IL-1β production during pathogen-induced macrophage death are likely to be critical to uncovering the bacterial infection mechanisms that promote colonization." (PMID 28848713, 2017). "As UBE2L3 affected pro-IL-1β protein in response to LPS, PAM3CSK4, and TNF, we asked whether it altered pro-IL-1β produced in response to natural bacterial infection." (PMID 28147281, 2017). "The increase in IL-1β mRNA after bacterial infection may be due to the up-regulation of gene expression as well as the proliferation and recruitment of IL-1β expressing cells in the tissues." (PMID 27706080, 2016). "Moreover, metformin administration to mice significantly increased the systemic levels of IL-1β and animal mortality upon bacterial infection." (PMID 28018360, 2016). "Thus, the IL-18 response in viral infections is responsible for hyperferritinemia, while bacterial infections are characterized by an IL-1β/IL-6 response, culminating in elevated plasma levels of CRP." (PMID 27977798, 2016). "In this study, we further investigated whether piperine administration reduced IL-1β release in C57BL/6 mice upon bacterial infection." (PMID 27812336, 2016). "Treatment with IL-1-β blockage is accepted to be lifesaving, because the disorder mimics severe bacterial infections and may result in death from development of systemic inflammatory response." (PMID 26100510, 2015). "IL-1β secretion by macrophages recruits additional macrophages and neutrophils into the lungs, and is an essential component of the innate immune response to bacterial infection." (PMID 26554712, 2015). "Thus, caspase-1 independent release of IL-1β occurred during bacterial infection of macrophages and RIP1 activation was at least in one instance suppressive of this." (PMID 26659062, 2015). "Furthermore, IL-1Ra suppresses LPS-induced IL-1β production and plays a protective role against bacterial infection." (PMID 26474296, 2015).
bacterial infection (continued). "Thus, we used a challenge with low dose of bacterial LPS to mimic secondary bacterial infection and to evaluate the role of inflammasome and IL-1β in this process." (PMID 24453977, 2014). "Indeed, in a study of human community acquired pneumonia, IL-1β was a predictive marker for bacterial infection." (PMID 24324838, 2013). "IL-1β has been ascribed a pro-bacterial role in some bacterial infection models, and thus p60 might conceivably benefit Lm by inducing IL-1β." (PMID 23028835, 2012). "THP-1 macrophages were treated with IL-1β neutralizing antibody during bacterial infection." (PMID 22558425, 2012). "This lack of increase may be the result of excluding patients with presumptive bacterial infections, because LPS is the main inducer for the synthesis of IL-1β." (PMID 21989210, 2011). "Despite an extensive literature search we could identify only a single report where IL-1β was shown to be deleterious in bacterial infections." (PMID 22241982, 2011). "In fact, upregulation of extracellular ATP has been observed in the context of bacterial infections and secretion of processed IL-1β Thus, prerequisites for caspase-1 activation and IL-1β processing/secretion in skin macrophages exposed to B. burgdorferi are likely in place." (PMID 20976193, 2010). "IL-1β, IL-6, IL-18, and tumor necrosis factor (TNF)-α are pro inflammatory cytokines, and procalcitonin (PCT) and C-reactive protein (CRP) are nonspecific markers of systemic inflammation that increase sharply during pathogenic infections including bacterial infections." (PMID 40532039, 2025). "Indeed, previous literature shows that genetic polymorphisms in innate immune signaling factors, such as IL-6, TLR2 and IL-1β may explain the variation in disease severity during bacterial infections in preterm and term newborns." (PMID 38562936, 2024). "Besides TNF-α and IL-6, also IL-1β drives protective immunity during bacterial infections." (PMID 38562936, 2024). "If proIL-1β expression is induced by LPS prior to bacterial infection or treatment with mycolactone, the resulting proIL-1β could be cleaved by activated caspase-1 and mature IL-1β could be readily released, along with the induction of necrotic cell death by mycolactone." (PMID 37910490, 2023). "The bcl6aamdu21/mdu21 mutants were also found to be less able to control bacterial infection, had elevated il1b and reduced survival, in agreement with data from Bcl6a knockout mice that showed increased inflammatory gene expression following LPS injection, including Il1b." (PMID 36389136, 2022). "M.tb has previously been shown to inhibit inflammasome activation and IL-1β processing, and a recent study demonstrated that CARD9, an inflammasome protein associated with fungal induction of proinflammatory cytokines, negatively regulated IL-1β production during bacterial infection." (PMID 36591308, 2022). "The GSDMD−/− mice presented decreased IL-1β and increased Cxcl1 secretion following S. aureus infection, suggesting that upon S. aureus challenge, promotion of IL-1β production or inhibition of Cxcl1 may be the key for the protective effect of GSDMD during bacterial infection." (PMID 34011393, 2021). "The improved resistance to bacterial infection in the PG-1 transgenic mice could be resulted from the direct bacteria-killing activities of PG-1, and the immunomodulatory effects of PG-1 via stimulating interleukin 1 beta secretion." (PMID 32994542, 2020). "In addition, we described that the mRNA expression levels of proinflammatory cytokines IL-8 and IL1-β increased significantly after bacterial infection, which were induced similarly in mammal gingival epithelial cells against bacterial pathogens, P. gingivalis and Lactobacillus acidophilus." (PMID 33072100, 2020). "In addition, IL-1β has been ascribed a probacterial role in some bacterial infection models." (PMID 33457411, 2020).
bacterial infection (continued). "Even though (a) IL-1β/IL-18 secretion might occur independently of pyroptosis and (b) caspase-1 or caspase-11 deletion is more severe than IL-1β/IL-18 ablation in some bacterial infections, usually cytokine release and cell death are overlapping events necessary for optimal host defense." (PMID 30459758, 2018). "Finally, we explored whether berberine augmented inflammasome activation and IL-1β secretion in vivo in the context of bacterial infection in the peritoneal cavity of mice, which is a commonly used bacterial infection model." (PMID 27980220, 2017). "As IL-1β release was increased by berberine treatment in the mouse model, we examined whether berberine increased neutrophil recruitment in the peritoneal cavity upon bacterial infection." (PMID 27980220, 2017). "To evaluate whether invasive potential differences between all the tested bacteria to cause varied stimulation effects on proinflammatory response, we further compared the expression level of TLR-2, Il-1β, and iNOS mRNAs during bacterial infection the MG-63 cells." (PMID 28800779, 2017). "Interleukin (IL)-1β, a pro-inflammatory cytokine, is intensely produced by activated macrophages and has a central role in the regulation of many inflammatory forms of cell death typically triggered by inflammasome-mediated caspase-1 activation during bacterial infection." (PMID 28848713, 2017). "Western blotting also demonstrated that bacterial infection increased both pro-IL-1β and mature IL-1β (17 kDa) expression in the colonic tissues, suggesting inflammasome activation in the colon, which might be infected by bacteria injection in the peritoneal cavity." (PMID 27812336, 2016). "In further support of this, metformin-treated mice had a marked increase in their serum levels of IL-1β at 4-h and 8-h time points when compared with controls (vehicle treated), indicating increased inflammasome activation in metformin-treated mice upon bacterial infection." (PMID 28018360, 2016). "Viral and bacterial infections increase expression of TNF-α, IL-1β, and other cytokines that stimulate NF-kB activation responsible for amplifying and driving expression of downstream cytokines/chemokines such as CXCL5." (PMID 40494897, 2025). "Bacterial infection induces endotoxin production, which stimulates macrophages to produce high levels of pro-inflammatory cytokines, including TNF-α, IL-6, and IL-1β." (PMID 39625293, 2025). "Following a mixed bacterial infection, the experimental groups showed significantly higher levels of NFκB, TLR4, IL-6, TNF-α, and IL-1β compared to the control group (p < 0.05)." (PMID 40136393, 2025). "In response to bacterial infections, pro-inflammatory cytokines including IL-8, IL-6, TNF-α, and IL-1β are released, triggering neutrophil recruitment and new neutrophil production via G-CSF." (PMID 40766078, 2025). "Anaerobic bacterial infections induce local and systemic increases of proinflammatory cytokines including TNF-α, IL-1β, and IL-6." (PMID 40552326, 2025). "Delayed wound healing can be attributed to a widespread inflammatory response primarily driven by bacterial infection, leading to failed macrophage polarization and excessive secretion of inflammatory factors such as TNF-α, IL-6, and IL-1β." (PMID 40051835, 2025). "Bacterial infection induced the activation of TrGSDMEa and CASP3/7 in pufferfish cells, resulting in pyroptosis accompanied with IL-1β production and maturation." (PMID 39219679, 2024). "In the presence of bacterial infection, serotonin plays a role in inhibiting the production of TNF-α stimulated by LPS and increasing the release of IL-1β by peripheral blood mononuclear cells." (PMID 38998045, 2024). "It is known that, in patients with bacterial infection, PCT blood levels increase in response to toxins and some cytokines (TNF-α, IL-6, IL-1β), and its level decreases dramatically in parallel with the success of the treatment." (PMID 39797227, 2024).
bacterial infection (continued). "The intensities of inflammatory indicators, like IL-1β, IL-6, and TNF-α, usually rise during bacterial infections as they are part of bacterial pathogenesis." (PMID 39338376, 2024). "Among PGES, mPGES-1 is an enzyme induced by the stimulation of inflammatory mediators such as IL-1β and TNF-α, mainly released by macrophages after tissue damage or bacterial infection." (PMID 36661522, 2023). "We conclude that α toxin by these two different mechanisms triggers the synthesis of pro-IL-1β and NLRP3 components, activation of capase-1, and secretion of mature IL-1β to defend against bacterial infection." (PMID 38089811, 2023). "On the other hand, since bacterial infection is one of the classic instigators of inflammation, we took innate immune-related genes (IFN-α, IFN-γ, and IL-1β) stimulated by LACpG10-HL into account in this study." (PMID 36232768, 2022). "As well-known inflammatory cytokines or chemokines, IL-1β, IL-8, IL-6, TNF-α and TLR4 are involved in various types of inflammatory responses, and play key roles in the inflammatory process during bacterial infection of bovine mammary glands." (PMID 36233122, 2022). "The western-blot results showed that knockdown of β-catenin enhanced the cleavage of Caspase-1, IL-1β and GSDMD at indicated time points after pyogenic bacterial infection." (PMID 36068223, 2022). "IL-1β and IL8 are the two main proinflammatory cytokines in fish, and they can balance the inflammatory response to bacterial infection." (PMID 35145928, 2022). "Their expression levels are dramatically elevated, resulting in an increase in the production of inflammatory cytokines such as IL-1β and TNF-α on bacterial infections in mammals." (PMID 36557603, 2022). "As a result, the expression of IL-1β and TNF-α proteins stimulated by the bacterial infection was improved following THSG, NAC, and apocynin treatment." (PMID 35453424, 2022). "Most of these chemokines and cytokines, such as CCL5, CCL22, IL-1β, and TNF-α, are critical to “pre-condition” the lungs to become invulnerable to bacterial infections or promote bacterial clearance during lung infections." (PMID 35677203, 2022). "PCT is synthesized in response to endotoxins or mediators, interleukin (IL)-1β, tumor necrosis factor (TNF)-α, and IL-6, during bacterial infections and has a strong correlation with the severity and extent of bacterial infections." (PMID 35547462, 2022). "BC contains many cytokines of relevance for immune modulation and cellular responses to stressors such as bacterial infection; these cytokines include TNFα, GMCSF, and interleukin (IL)-1β, -6, and -10." (PMID 33809940, 2021). "In the bacterial infection model (LPS), SNV significantly reduced IL1β expression, while VIP increased IL6 expression." (PMID 34025407, 2021). "Following bacterial infection, BDNF pretreatment reduces the expression of TNF-α, IL-16, IL-1β, and the NFκB pathways, and increases IL-10 and Trk expression." (PMID 34831151, 2021). "Increased expression of caspase-1, secretion of IL-1β (facilitated by caspase-1), and increased substrate of GSDMD, are frequently reported in bacterial infection-related pyroptosis and sterile inflammation." (PMID 34360821, 2021). "LPS endotoxins are widely used as experimental models of systemic bacterial infection and trigger inflammatory factors such as TNF-α, IL-1β and IL-6." (PMID 33557833, 2021). "Similar findings were observed in the sera levels of IL1-β, TNF-α, and IFN-γ in pigs with viral respiratory disease and in cattle with bacterial infection." (PMID 34944151, 2021). "Whereas LPS, widely used to mimic bacterial infections in vitro, evoked distinct pro-inflammatory responses in HBMEC, expressed by mRNA and protein increases for CXCL5, IL-1α, IL-1β, IL-6, IL-8, MCP-1, MCP-3, and TNF-α, Ureaplasma spp." (PMID 31336668, 2019).